ZKSCAN7 (zinc finger with KRAB and SCAN domains 7)
Description:
May be involved in transcriptional regulation.
Synonyms: ZNF167; ZNF448; ZNF64; FLJ12738; ZSCAN39; ZFP
Tractability: PROTAC: UniProt records ubiquitination sites on it; ubiquitination databases record sites on it.
Gene: Protein-coding gene on chromosome 3 (44,555,193 to 44,594,173, forward strand). Ensembl gene ENSG00000196345.
Subcellular location: Nucleus
Subcellular location (Human Protein Atlas): Cytosol; Nuclear speckles
Pathways (Reactome):
Gene expression (Transcription): Generic Transcription Pathway
Gene Ontology:
Molecular function: protein binding; DNA-binding transcription factor activity, RNA polymerase II-specific; RNA polymerase II cis-regulatory region sequence-specific DNA binding
Biological process: regulation of transcription by RNA polymerase II; regulation of DNA-templated transcription
Cellular component: cytosol; nucleus
Genetic constraint (gnomAD): Loss-of-function variants: 39 observed, 63.32 expected, observed/expected ratio (o/e) 0.62, 90% interval 0.48 to 0.8. The upper end of that interval is the gene's LOEUF score, 0.8, which puts it in group 3 of 6, group 1 being the genes least tolerant of losing a copy. Missense variants: 788 observed, 895.81 expected, observed/expected ratio (o/e) 0.88, 90% interval 0.83 to 0.93. Synonymous variants: 311 observed, 315.93 expected, observed/expected ratio (o/e) 0.98, 90% interval 0.9 to 1.08.
Homologues: Orthologues: chimpanzee ZKSCAN7 (99% identical), macaque ZKSCAN7 (94% identical), pig ZKSCAN7 (83% identical), rat Zkscan7 (72% identical), mouse Zkscan7 (69% identical). Paralogues in human: ZNF852 (64% identical), ZNF287 (40% identical), ZNF527 (31% identical), ZNF34 (29% identical), ZNF214 (29% identical), ZNF572 (29% identical), ZNF17 (29% identical), ZNF333 (29% identical), ZNF285 (28% identical), ZNF416 (28% identical), ZNF774 (28% identical), ZNF530 (27% identical), and 38 more.
Diseases named in the same sentence as ZKSCAN7 in open-access papers:
ZKSCAN7 is named in the same sentence as 8 diseases in open-access papers, as found by Europe PMC text mining. Sharing a sentence is not in itself a finding about the gene and the disease.
ZKSCAN7 shares sentences with these, for which no sentence is quoted: cancer (4 papers); tumor (2); viral infection (2); colon cancer (1); ischemic stroke (1); malaria (1); Obesity (1); oropharyngeal squamous cell carcinoma (1).